YLPM1 (YLP motif containing 1)
Description:
Plays a role in the reduction of telomerase activity during differentiation of embryonic stem cells by binding to the core promoter of TERT and controlling its down-regulation.
Synonyms: C14orf170; ZAP3; ZAP; PPP1R169; ZAP113
Tractability: PROTAC: UniProt records ubiquitination sites on it; ubiquitination databases record sites on it; its protein half-life has been measured.
Gene: Protein-coding gene on chromosome 14 (74,763,316 to 74,859,435, forward strand). Ensembl gene ENSG00000119596.
Subcellular location: Nucleus; Nucleus speckle
Subcellular location (Human Protein Atlas): Nuclear speckles
Gene Ontology:
Molecular function: protein binding; RNA binding
Biological process: regulation of telomere maintenance
Cellular component: nuclear speck; nucleus
Genetic constraint (gnomAD): Loss-of-function variants: 94 observed, 201.04 expected, observed/expected ratio (o/e) 0.47, 90% interval 0.4 to 0.56. The upper end of that interval is the gene's LOEUF score, 0.56, which puts it in group 2 of 6, group 1 being the genes least tolerant of losing a copy. Missense variants: 2,563 observed, 2,688.6 expected, observed/expected ratio (o/e) 0.95, 90% interval 0.92 to 0.99. Synonymous variants: 973 observed, 934.34 expected, observed/expected ratio (o/e) 1.04, 90% interval 0.99 to 1.1.
Homologues: Orthologues: chimpanzee YLPM1 (99% identical), macaque YLPM1 (99% identical), dog YLPM1 (96% identical), pig YLPM1 (95% identical), rat Ylpm1 (89% identical), mouse Ylpm1 (89% identical), guinea pig YLPM1 (84% identical), rabbit YLPM1 (78% identical), tropical clawed frog ylpm1 (42% identical), zebrafish ylpm1 (33% identical), Drosophila melanogaster ZAP3 (17% identical).
Diseases named in the same sentence as YLPM1 in open-access papers:
YLPM1 is named in the same sentence as 10 diseases in open-access papers, as found by Europe PMC text mining. Sharing a sentence is not in itself a finding about the gene and the disease. The quoted sentences say what the papers report.
depression (2 papers, 2021 to 2024). "For example, among the candidate genes were known susceptibility loci for diabetes (PTPN22, CEP68, RREB1, TCF7L2), coronary artery disease (PSRC1, UNC5C, LPLA), depression (MAD1L1, YLPM1) and insomnia (NMT1)." (PMID 38541061, 2024).
HCMV infection (1 paper, 2024). "Our findings indicate that HCMV infection disrupts PP1 function through the temporal dysregulation of at least nine recognized regulatory subunits, PPP1R10, PPP1R7, YLPM1, PPP1R11, PPP1R9A, PPP1R8 (NIPP1), PPP1R9B, PPP1R12C, and URI1." (PMID 39772267, 2024).
psoriasis (1 paper, 2024). An autoimmune condition characterized by red, well-delineated plaques with silvery scales that are usually on the extensor surfaces and scalp. "The plot clearly illustrates elevated gene expression of the hub genes in the psoriasis group, with the exception of the YLPM1 gene." (PMID 38791423, 2024).
YLPM1 also shares sentences with these, for which no sentence is quoted: diabetes (2 papers); congenital heart disease (1); coronary artery disease (1); insomnia (1); kidney diseases (1); Obesity (1); Stroke (1).